OFD1 (OFD1 centriole and centriolar satellite protein)
Diseases named in the same sentence as OFD1 in open-access papers (continued):
Sharing a sentence is not in itself a finding about the gene and the disease.
Joubert syndrome 10 (5 papers, 2016 to 2023). Any Joubert syndrome in which the cause of the disease is a mutation in the OFD1 gene. "OFD1 is linked to ciliary dysfunction (Joubert syndrome 10, X-linked recessive)." (PMID 34768622, 2021).
breast carcinoma (4 papers, 2021 to 2025). "To explore the applicability of OFD1 inhibition in other BRCA-associated cancer types with BRCA1/2 wild-type genotypes, we generated OFD1-inducible knockdown cell lines in MDA-MB231 breast cancer cells, PC3 prostate cancer cells, and A2780 ovarian cancer cells." (PMID 40764600, 2025). "We have further validated the cell growth defects upon OFD1 inhibition in five cancer cell lines, including colon cancer (HT-29), lung cancer (A549), pancreatic cancer (PANC1), breast cancer (MDA-MB-231), and renal cancer (ACHN)." (PMID 36973243, 2023). "Fusion partners of FGFR2 reported specifically in breast cancer are AFF3, CASP7 and CCDC6, while partners identified in other cancers include TACC and KIAA family members, PPHLN1, NTRK1, BICC1, AHCYL1, OFD1 and SLC45A3." (PMID 34344433, 2021).
cognitive defects (3 papers, 2014 to 2024). "OFD1 is a rare X-linked dominant ciliopathy associated with congenital malformations such as cleft palate, tongue lobulation, cognitive impairment, and digital anomalies." (PMID 39291187, 2024). "Our results indicate that >68% of OFD1 cases from our selected cohort present some form of cognitive impairment." (PMID 24884629, 2014).
glioblastoma (3 papers, 2021 to 2023). The most malignant astrocytic tumor (WHO grade IV). "Compared with normal tissues, the expression of OFD1 aberrantly increased in multiple cancers, including colorectal cancer, glioblastoma, renal cancer, liver cancer, lung cancer, and prostate cancer." (PMID 36973243, 2023). "This was in agreement with previous observations that OFD1 is part of a PKA interaction network identified in a collection of cancer cells, glioblastoma tissues and lung cancer." (PMID 33934390, 2021).
polycystic kidneys (3 papers, 2014 to 2021). "Orofacial digital type I syndrome (OFDI) is an X‐linked congenital ciliopathy caused by mutations in the OFD1 gene and characterized by malformations of the face, oral cavity, digits and, in the majority of cases, polycystic kidney disease." (PMID 33934390, 2021). "Deletion of the Ofd1 gene (Ofd1Δ4-5/+-) in mice causes missing/supernumerary teeth, enamel hypoplasia, and polycystic kidney disease analogous to human oral-facial-digital syndrome type 1." (PMID 25180832, 2014). "Systemic manifestations of OFD1 mutations include polycystic kidneys that resemble those caused by mutations in the PKD1 or PKD2 genes associated with autosomal dominant polycystic kidney disease (ADPKD)." (PMID 25180832, 2014). "Mutation of the X-linked oral-facial-digital syndrome type 1 (OFD1) gene is embryonic lethal in males and results in craniofacial malformations and adult onset polycystic kidney disease in females." (PMID 25180832, 2014). "OFD1 patients with polycystic kidneys have a higher likelihood of developing renal failure." (PMID 27651963, 2016).
retinal degeneration (3 papers, 2016 to 2022). Degeneration of the retina. "The altered expression level of Ofd1 with disease progression in both models indicated that Ofd1 was closely linked to retinal degeneration." (PMID 27196396, 2016). "The present study is the first study to examine Ofd1 localization and its cilia associated function in retina tissue, and it also further investigates the potential mechanism underlying retina degeneration in animal model." (PMID 27196396, 2016). "Ofd1, combined with ciliary associated and Wnt signaling pathway genes were involved in both retinal degeneration rat models." (PMID 27196396, 2016). "This highly conserved domain is predicted to bind to microtubules as well as proteins linked to retinal degeneration and ciliary trafficking, such as CEP290, OFD1, and LCA5." (PMID 36233334, 2022). "These two retinal degeneration models are completely different, and thus it was reasonable to propose that Ofd1, other cilia-related genes, and Wnt signaling pathway genes are differentially expressed." (PMID 27196396, 2016).
X-linked inherited disease (3 papers, 2014 to 2024). "OFD1 (OMIM #311200) is an X-linked inherited disease by CXORF5 characterized by the malformation of the face, oral cavity, hands, and feet." (PMID 37629084, 2023). "Oral-facial-digital syndrome type 1 (OFD1; OMIM #311200) is an X-linked inherited disease characterized by the malformation of the face, oral cavity, hands and feet caused by heterogeneous mutations in the OFD1 gene also known as CXORF5." (PMID 25180832, 2014).
cyst (2 papers, 2016 to 2023). A sac-like closed membranous structure that may be empty or contain fluid or amorphous material. "ADPKD differs from OFD1 based on larger kidney size, distribution of cysts, tendency to larger cyst size, and origin of the cysts which are tubular in ADPKD." (PMID 27651963, 2016). "Based on the rescued phenotype of kidney cyst formation in ik morphants co-injected with ofd1 mRNA, we inferred that co-injection of ofd1 mRNA into ik morphants would also moderate the impairment of kidney development or cyst formation and affect foxj1a expression." (PMID 37898820, 2023). "In addition, cyst formation observed in ik morphants by approximately 53% was reduced to 21.4% in ik morphants co-injected with ofd1 mRNA." (PMID 37898820, 2023).
Kidney Cyst (2 papers, 2023 to 2024). Abnormal fluid filled sac within the kidney, either acquired or congenital. "Of 157 patients, 7 had parents with simple kidney cyst (1 with the IFT140 pathogenic variant, 3 with the PKD1 or PKD2 pathogenic variant, 1 with the OFD1 pathogenic variant, and 2 without pathogenic variants)." (PMID 39291187, 2024).
lung carcinoma (2 papers, 2021 to 2023). "Consistent with the mRNA transcription pattern, OFD1 protein levels also increased in colon adenocarcinoma (COAD) and lung cancer." (PMID 36973243, 2023).
pancreatic cancer (2 papers, 2023 to 2025). "Our study using shRNA specific for OFD1 in the treatment of established tumors suggests that OFD1 loss could robustly inhibit tumor growth of pancreatic cancer cells." (PMID 36973243, 2023). "In this study, we observed a marked overexpression of OFD1 in pancreatic cancer tissues compared with adjacent normal tissues, as confirmed by both tissue microarrays from PDAC patients and TCGA datasets." (PMID 40764600, 2025). "OFD1 inhibition synergizes with olaparib in pancreatic cancer xenograft, spontaneous, and patient-derived xenograft models, and in other BRCA-associated cancer models." (PMID 40764600, 2025). "To investigate how OFD1 knockdown sensitizes pancreatic cancer cells to olaparib, we conducted RNA sequencing (RNA-seq) on the pancreatic cancer cell lines PANC1, MIA PaCa-2, PATU8988T following OFD1 knockdown." (PMID 40764600, 2025). "Analysis of multiple published PDAC datasets showed that OFD1 was significantly overexpressed in pancreatic cancer tissues compared to normal pancreatic tissues." (PMID 40764600, 2025). "To further evaluate the role of OFD1 in PDAC tumorigenesis, we investigated the inhibitory effects of OFD1 knockdown in a panel of pancreatic cancer cell lines." (PMID 40764600, 2025). "A cellular viability screen using an FDA-approved drug library was conducted on MIA PaCa-2, a pancreatic cancer cell line moderately sensitive to OFD1 knockdown." (PMID 40764600, 2025). "To further investigate the role of OFD1 in pancreatic cancer progression, we analyzed OFD1 expression in the publicly available GEO database." (PMID 40764600, 2025). "Here, in preclinical models of pancreatic cancer, the authors identify OFD1 as a transcriptional regulator of BRCA1 via the DREAM complex and as a potential therapeutic target in combination with PARP inhibition." (PMID 40764600, 2025). "To investigate the potential synergistic effect of OFD1 inhibition and olaparib treatment in pancreatic cancer, we used two pancreatic PDX models derived from patients with BRCA1/2 wild-type tumors." (PMID 40764600, 2025). "Although some pancreatic cancer cell lines were sensitive to OFD1 inhibition, as we previously reported, others such as MIA PaCa-2, SW1990, HPAC, PATU8988T, BXPC3 and PANC1005 were considerably less sensitive." (PMID 40764600, 2025). "We further confirmed the effect of OFD1 knockdown on BRCA1 downregulation in several other pancreatic cancer cell lines (, c)." (PMID 40764600, 2025). "In our recent study, we identified a potential role for OFD1 in cancer, particularly in pancreatic cancer, where its knockdown significantly inhibited subcutaneous tumor growth." (PMID 40764600, 2025). "We identify OFD1 as a positive regulator of BRCA1 in human pancreatic cancer cells and specimens, with its overexpression correlating with poor prognosis." (PMID 40764600, 2025). "We further evaluated the effects of OFD1 depletion on tumorigenesis and progression in vivo, using mouse xenograft models with highly malignant pancreatic cancer, colon cancer, and triple-negative breast cancer cells." (PMID 36973243, 2023). "Pancreatic cancer cell line PANC-1 with stably expressed Tet-inducible control shRNA or OFD1 shRNA were subcutaneously inoculated into NOD/SCID mice." (PMID 36973243, 2023). "To explore this, we conducted a chemical screening to identify compounds that could synergize with OFD1 inhibition to kill pancreatic cancer cells." (PMID 40764600, 2025). "Given that OFD1 is predominantly localized in the cytoplasm of pancreatic cancer cells, we hypothesized that OFD1 regulates E2F4 translocation through interaction in the cytoplasm." (PMID 40764600, 2025). "Interestingly, we observed a heterogeneous response to OFD1 inhibition in different pancreatic cancer cell lines ex vivo." (PMID 40764600, 2025).
pancreatic cancer (continued). "Furthermore, colony formation assays confirmed the synergistic effects of OFD1 knockdown and olaparib treatment in multiple pancreatic cancer cell lines, including MIA PaCa-2, SW1990, PATU8988T, and PANC1005." (PMID 40764600, 2025). "We hypothesized that although OFD1 depletion alone is insufficient to kill these pancreatic cancer cells, it may sensitize them to other anticancer therapies." (PMID 40764600, 2025). "Furthermore, depletion of OFD1 sensitizes pancreatic cancer cells and tumor models to PARPi." (PMID 40764600, 2025). "The PDAC cohorts were classified into strong, moderate and weak expression groups based on their IHC intensity and area, OFD1 and BRCA1 expression showed a strong correlation in these pancreatic cancer samples." (PMID 40764600, 2025). "In this study, we identify a strong positive correlation between OFD1 and BRCA1 expression in pancreatic cancer." (PMID 40764600, 2025). "The interaction between recombinant OFD1 and E2F4 was further validated by endogenous immunoprecipitation (IP) in three pancreatic cancer cell lines and an in vitro pulldown assay (, j)." (PMID 40764600, 2025). "Next, we investigated the mechanism by which OFD1 regulates BRCA1 transcription, GSEA molecular signatures analysis in OFD1 knockdown pancreatic cancer cells revealed significant enrichment of genes regulated by the DREAM complex in both PANC1 and MIA PaCa-2 cells upon OFD1 knockdown." (PMID 40764600, 2025). "Similarly, to the pancreatic cancer xenografts, colon cancer xenografts from HT-29 cells and triple-negative breast cancer xenografts from MDA-MB-231 cells also relied on OFD1." (PMID 36973243, 2023).
autism (1 paper, 2023). Persistent deficits in social interaction and communication and interaction as well as a markedly restricted repertoire of activity and interest as well as repetitive patterns of behavior. "We report on a three-year-old girl with a complex phenotype that includes oral malformations, severe speech delay, dysmorphic features, developmental delay, autism, and bilateral periventricular nodular heterotopia, presenting a de novo pathogenic variant in the OFD1 gene." (PMID 36833254, 2023). "We report on a three-year-old girl with a complex phenotype that includes oral malformations, severe speech delay, dysmorphic features, developmental delay (DD), autism, and bilateral periventricular nodular heterotopia presenting a de novo pathogenic variant in the OFD1 gene." (PMID 36833254, 2023).
behavioral disorders (1 paper, 2021). "Three out of seven genes (i.e., HTR2C, MAOA, and OFD1) were previously associated with behavioral disorders in humans, such as aggressive behavior, antisocial personality, and low frustration tolerance." (PMID 33800722, 2021).
cleft lip (1 paper, 2017). Congenital defect in the upper lip where the maxillary prominence fails to merge with the merged medial nasal prominences. "Only one SNP, rs6527959, represented OFD1 in the GWAS dataset, and this SNP only achieved moderate significance for isolated cleft lip only (CLO) in European males (p-value 0.0091), hardly convincing in light of the number of models, endpoints and ethnicities tested." (PMID 28877219, 2017).
conductive hearing loss (1 paper, 2024). "Variants in CCDC114 cause sensorineural hearing loss (SNHL), while variants in CCNO, CDH3, DNAH5 and OFD1 cause conductive hearing loss (CHL)." (PMID 38818043, 2024).
Duchenne muscular dystrophy (1 paper, 2022). Duchenne muscular dystrophy (DMD) is a neuromuscular disease characterized by rapidly progressive muscle weakness and wasting due to degeneration of skeletal, smooth and cardiac muscle. "The OFD1 gene is located in the area between the pseudoautosomal boundary and the Duchenne muscular dystrophy (DMD) gene on the short arm of chromosome X. OFD1 encodes a component of the centrioles controlling mother and daughter centriole length." (PMID 36704348, 2022).
end-stage renal disease (1 paper, 2016). "We present a male patient with OFD1 mutation who lacks the classic OFD1 phenotype who presented with end-stage renal disease without evidence of polycystic changes within the kidneys." (PMID 27651963, 2016).
endometrial cancer (1 paper, 2023). Primary or metastatic malignant neoplasm involving the endometrium (mucous membrane that lines the endometrial cavity). "Excessive accumulation of OFD1 due to dysregulation of autophagy causes fewer ciliated cells in the endometrial cancer tissues." (PMID 37485393, 2023).
glioma (1 paper, 2022). A benign or malignant brain and spinal cord tumor that arises from glial cells (astrocytes, oligodendrocytes, ependymal cells). "After single or repeated TTFields exposure, we plated cells in serum for 4 days, fixed, and immunostained for ARL13B alone or combined with pericentriolar material 1 (PCM1), another protein that clusters around the basal body and centrioles in glioma cells, or OFD1." (PMID 35359402, 2022).
lung disorder (1 paper, 2020). A disease involving the lung. "Several genes associated with monogenetic lung disorders were also dysregulated in specific cell populations of smokers, including PCD (OFD1 – down-regulated in ciliated cells) and surfactant deficiency (SFTPB - up-regulated in ionocytes)-related genes." (PMID 32727470, 2020).
male infertility (1 paper, 2025). The inability of the male to effect fertilization of an ovum after a specified period of unprotected intercourse. "Several satellite genes have been associated with male infertility and sperm flagellum defects in humans and mice, including PCM1, CEP131, BBS4, OFD1, CEP290, CCDC13, etc.." (PMID 40801568, 2025).
Meckel-Gruber syndrome (1 paper, 2014). "Interestingly, two OFDVI patients were reported to have a homozygous mutation in TMEM216, a gene implicated in JSRD and Meckel-Gruber syndrome (MKS), and a mutation in the OFD1 transcript has been reported in an OFDVI case." (PMID 24884629, 2014).
medulloblastoma (1 paper, 2022). A malignant, invasive embryonal neoplasm arising from the cerebellum. "In medulloblastoma, loss of cilia mediated due to ablation of OFD1 can lead to smoothened (SMO) inhibitor treatment resistance and formation of “persister-like” states that support tumor recurrence." (PMID 35359402, 2022).
Miscarriage (1 paper, 2015). A pregnancy that ends at a stage in which the fetus is incapable of surviving on its own, defined as the spontaneous loss of a fetus before the 22th week of pregnancy. "TRAPPC2 and OFD1 had increased RNA and protein expression in miscarriage 9-3B with a gain of Xp22.2." (PMID 25674159, 2015). "Three genes, OFD1, TRAPPC2 and TIMP2 out of 14 selected for expression analysis had altered mRNA and protein expression in cultured miscarriage chorionic villi cells." (PMID 25674159, 2015).
optic neuritis (1 paper, 2017). Optic neuritis is inflammation of the optic nerve, the nerve that carries the visual signal from the eye to the brain.The conditionmay cause sudden, reduced vision in the affected eye(s). "The responsibility of the variant for the reduced expression of OFD1 and the episode of optic neuritis need to be further confirmed." (PMID 28191358, 2017).
oropharyngeal squamous cell carcinoma (1 paper, 2022). "In patients with oropharyngeal squamous cell carcinoma, HPV may regulate OFD1 expression and primary cilia formation, thereby influencing tumor progression and making this protein a possible target for treatment." (PMID 36467412, 2022).
Retinal atrophy (1 paper, 2021). A nonspecific term denoting wasting, especially as a result of degeneration, of the retinal pigment epithelium (RPE) and neurosensory retinal cells. "Interestingly, retinal atrophy and thin optic nerves have been detected in a small cohort of females with OFD1 variants." (PMID 33825116, 2021).
Retinal coloboma (1 paper, 2021). A notch or cleft of the retina or choroid, located vertically below the optic disc. "Ofd1 inactivation by injection of antisense morpholinos in zebrafish causes the incomplete fusion of the choroid fissure of the eye resulting in a retinal coloboma similar to MGDA." (PMID 33825116, 2021).
syndactyly (1 paper, 2018). A disease characterized by the presence of syndactyly, including syndromic and non-syndromic forms. "In this study, by using whole exome sequencing (WES), a novel OFD1 splicing mutation (c.2488+2T>C) was identified in a male fetus with suspected Dandy-Walker variant (DWV) and syndactyly, for whom abnormal karyotype and pathogenic CNV have been excluded." (PMID 30581852, 2018).
Ventriculomegaly (1 paper, 2014). An increase in size of the ventricular system of the brain. "One of these was the de novo 21 kb deletion g.13770686_13791294del on Xp22.2 found in F14, a female fetus with ventriculomegaly and agenesis of the corpus callosum, This CNV removes most of the gene OFD1 (MIM 300170)." (PMID 24476948, 2014).